KRAS (KRas proto-oncogene, GTPase)
Diseases named in the same sentence as KRAS in open-access papers (continued):
Sharing a sentence is not in itself a finding about the gene and the disease.
tumor (continued). "However, recent studies have shown that NSCLC patients with KRAS mutations have different degrees of sensitivity to ICIs treatment, and KRAS mutations are significant in enhancing PD-L1 expression, promoting T cell infiltration, and enhancing tumor immunogenicity." (PMID 35581376, 2022). "KRAS activation leads to the loss of p16, accelerating NADH oxidation and supporting increased glycolysis through the production of NAD+ to support tumor growth." (PMID 36465353, 2022). "However, despite the loss of KRAS transcripts seen 2 weeks after the Dox was discontinued, these cells still showed elevated YB-1 protein levels that were similar to those evident in the tumours obtained from cells in which KRASG12D expression had been sustained." (PMID 34294889, 2022). "In patients with NSCLC, alteration of KRAS/STK11 was found to have influence on tumor microenvironment and decrease PD-L1 expression levels, suggesting a lower response rate to ICIs and poorer prognosis 70,71." (PMID 35069896, 2022). "Two new molecules, sotorasib and adagrasib were found to decrese the phosphorylation of ERK and promote the tumor regression in mice bearing KRAS G12C-mutant NSCLC tumors." (PMID 36230757, 2022). "In contrast, BRAF and KRAS alterations correlated with decreased tumor amplification burden in the TCGA dataset." (PMID 36171565, 2022). "SIRT1, an oncogene or tumor suppressor, was found decreased by KRAS in a PI3K and MEK dependent way, which contributes to lung carcinogenesis." (PMID 36619616, 2022). "It was known that KRAS/NRAS-activating mutations promote the activation of both MEK-ERK and AKT-mTOR signaling in tumor cells." (PMID 35395857, 2022). "In parallel with the in vitro data, the combination treatment significantly increased β-TrCP and GSK-3β expressions and reduced KRAS expression levels in the tumor tissues of these mice." (PMID 35305671, 2022). "In fact, cell-based studies revealed a diminished glycolytic flux in KRAS mutant tumor cells in which KRAS4A was silenced with CRISPR/Cas9." (PMID 36393833, 2022). "In the context of cancer, several known tumor suppressor and oncogenic miRNAs have been found to interact with KRAS." (PMID 35139853, 2022). "Here we report a first-in-class molecule, a novel, single domain camelid VHH antibody (15 kDa), SBT-100, that binds to both STAT3 and KRAS and can penetrate the tumor cell membrane, and significantly inhibit cancer cell growth." (PMID 35886918, 2022). "In the KRAS mutant tumor model, simvastatin treatment activated the dendritic cell-mediated CD8+ T cells immunity." (PMID 35955474, 2022). "Mutated KRAS affects cell signal transduction by binding with the GTP and becoming activated, activating the downstream tumor signaling pathway, significantly improving cell proliferation ability and influencing immune targeting." (PMID 36505791, 2022). "In contrast with the previous thought of KRAS mutant independency from upstream RTK, recent data demonstrate that the genetic abrogation of EGFR resulted in impaired tumor growth of KRAS mutant NSCLC models." (PMID 36358848, 2022). "Restoration of tumor-suppressor miR-126 levels sufficient to effect decreases in downstream KRAS levels will only be achieved when delivering sufficient functionally active miR-126 to enable necessary interactions with RNA-induced silencing complex (RISC)." (PMID 36451861, 2022). "A major research breakthrough has been achieved using a small molecule AMG 510 as a potential mutant KRAS(G12C) inhibitor with high specificity and sensitivity to effectively block tumor growth in vivo." (PMID 35630522, 2022).
tumor (continued). "A preclinical study suggested that KRAS G12C inhibition can swiftly change the tumor’s immune-suppressive microenvironment to the one that allows effective anti-tumor immunity." (PMID 36741723, 2022). "This chemical was initially designed as an anticancer drug that binds to the mutant KRAS gene and was shown to exhibit tumor growth inhibition in mouse xenograft studies." (PMID 35205697, 2022). "It evaluates the presence of KRAS, NRAS, and BRAF mutations, nodal status, CEA/CA19-9 levels, and the modified Tumor Burden Score to predict cancer recurrence." (PMID 36428606, 2022). "The results showed that high APOBEC3G was most closely related to upregulating the KRAS signaling pathway, which played important roles in the cell cycle control of tumor initiation." (PMID 36144542, 2022). "KRAS signaling can affect tumor proliferation by two independent pathways: one is the MAPK/ERK and PI3K/AKT signaling pathway and the other is YAP1 and c-myc, both of which were involved in cell cycle actions." (PMID 36144542, 2022). "Sulfasalazine is well characterized for selectively suppressing the proliferation of CD44v-expressing cancer stem-like cells and KRAS-mutant cancer cells and markedly inhibiting tumor growth in several pre-clinical cancer models." (PMID 36338517, 2022). "One of the mechanisms in which mutant KRAS contributes to tumor progression is through activation of the phosphoinositide 3-kinase (PI3K) /protein kinase B (AKT)/mTOR pathway by binding to the p110α subunit of PI3K, causing a procarcinogenic signaling cascade." (PMID 36090030, 2022). "Of note, it has been shown that NSCLC with G12C, G12V, and G12A mutations are typical of smoking-associated tumors with high tumor mutation burden (TMB), with the exception of the KRAS-G12D point mutation." (PMID 36061356, 2022). "HK2 is required for tumor initiation in the KRAS-driven NSCLC mouse model, and the deletion of HK2 prolongs the survival of mice." (PMID 36532721, 2022). "A limitation of our findings is that it is unclear why BRAF and KRAS alterations would correlate with a decreased tumor amplification burden." (PMID 36171565, 2022). "The tumor volume reduced by 46%, the tumor volume decreased by 30%, and the expression of KRAS mutant protein decreased dramatically in A549 mice treated with Adv-Cas9-sgG12S." (PMID 35620280, 2022). "Our results suggest the need to develop targeted therapies for KRAS-mutant NSCLC or combine the targeting of oncogenic KRAS in addition to other therapeutic agents specific to the molecular profile of the tumor." (PMID 35877239, 2022). "Fusion events involving KRAS have also been reported in TNBC, while NRAS mutations ranked among those that most impacted tumor transcriptional profiles." (PMID 36358725, 2022). "Histone deacetylase 5 (HDAC5)-induced bypass promotes macrophage recruitment into the TME and enables tumor recurrence following the extinction of KRAS (G12D)." (PMID 35922812, 2022). "The targeted therapies are tailored to the patient based on the specific genetic background of the tumor (e.g., mutation or altered expression of EGFR, KRAS, BRAF, PIK3CA, PTEN, HER2, or gene fusion of ALK, ROS1, RET)." (PMID 35205667, 2022). "Accordingly, increasing the DHA uptake can disrupt tumor redox homeostasis and kill KRAS mutant cells." (PMID 36619305, 2022).
tumor (continued). "Treatment with metformin in KRAS wildtype patient-derived xenograft (PDX) models had a minor antitumor effect but metformin treatment inhibited KRAS G12D tumor growth significantly." (PMID 36048281, 2022). "In this context, it is also significant that KRAS-driven tumours express higher levels of ERBB ligands, in particular amphiregulin and TGFα." (PMID 35971826, 2022). "Results showed that circulating tumor cells have not only the same mutated driver genes (such as APC, KRAS, or PIK3CA) with the primary and metastatic lesions but also new variant genes." (PMID 35799608, 2022). "In contrast, the concordance of KRAS mutations between PPE and paired neoplasia tissues was 91.67% in group 3, which was statistically higher than either group 1(1/4, 25.00%) or 2 (1/2, 50.00%) (P < 0.05)." (PMID 35796805, 2022). "Cas9-sgG12S suppressed the proliferation of tumor cells by inhibiting the production of the KRAS (G12S) protein in A549 cells, as well as the phosphorylation levels of downstream molecules Akt and ERK." (PMID 35620280, 2022). "YAP/TAZ integrate various oncogenic signaling pathways such as EGFR, TGFβ, Wnt, PI3K, GPCR, and KRAS, and are instrumental for tumor initiation, progression, and chemoresistance." (PMID 35163776, 2022). "In an in vivo KRAS G12C cell-derived xenograft model, oral administration of a combination of selinexor and sotorasib was demonstrated to reduce tumor burden and enhance survival." (PMID 35573474, 2022). "SOST interacted with STAT3 to enhance the TGF-β/KRAS signaling, increasing both tumor growth and bone metastasis." (PMID 36581888, 2022). "In the context of KRAS G12C inhibitors, pre-clinical studies highlighted that either sotorasib or adagrasib have enhanced anti-tumor efficacy when combined with anti- PD-1/PD-L1 therapy." (PMID 35251972, 2022). "Restoration of Lkb1 in oncogenic KRAS-driven lung tumors suppressed proliferation and led to tumor stasis." (PMID 35228570, 2022). "The blue line represents the KRAS-mutated tumours (mutKRAS) and the green dotted line represents the BRAF-mutated (mutBRAF) tumours." (PMID 34887523, 2022). "High STING tumor expression correlates with improved survival, early‐stage disease, and EGFR and KRAS mutations." (PMID 35099823, 2022). "Increased expression levels of KSR make tumor cells less dependent on KRAS signaling and thus possibly less responsive to KRAS inhibitors." (PMID 35313064, 2022). "In summary, we conducted a thorough investigation to explore the prognostic values of KRAS as a clinical biomarker, thus providing useful in-depth information for tumor-targeting therapy." (PMID 35563733, 2022). "In a mouse lung cancer model and in a KRAS-mutant human lung adenocarcinoma cell line (A549), elastase-induced degradation of insulin receptor substrate 1 leads to increased proliferation of tumor cells in both settings." (PMID 35504900, 2022). "KRAS G12D and G12V mutant tumours are significant challenges in cancer therapy due to high resistance to the treatment." (PMID 36619305, 2022).
tumor (continued). "It has been well-established that KRAS influences tumor inflammation and the immune response, and consequently affects tumor initiation, invasion, and metastasis." (PMID 35563733, 2022). "Further, GLUT1 overexpression is sufficient to suppress tumor growth in in vitro and in vivo models of KRAS mutant cancers via disrupting redox homeostasis." (PMID 36619305, 2022). "We observed the dysregulation of the DNA methylation of KRAS in cancers and discovered that numerous oncogenic and tumor-suppressive transcription factors bind the KRAS promoter region." (PMID 35563733, 2022). "The present results demonstrate that special vulnerabilities of KRAS-triggered tumor cells can be exploited successfully in drug combinations targeting different pathways." (PMID 36048281, 2022). "The search for inhibitors of SOS1 has yielded four compounds so far, namely BAY-293, MRTX0902, BI-3406 and BI-1701963, that inhibit KRAS-dependent tumor growth in vitro and in xenograft models." (PMID 36048281, 2022). "Three patients had KRAS wild-type (WT) tumor in the primary tissue and KRAS mutant (MT) tumor (two patients had KRASG12A and one patient had KRASG13D mutations) in the metastatic tissue." (PMID 35592200, 2022). "Hatley and colleagues found that miR-21 overexpression in G12D-mutant KRAS mouse NSCLC models enhanced tumor formation, and subsequent deletion of miR-21 led to a significant decrease in total tumor mass in proportion to normal lung area." (PMID 36139366, 2022). "Studies with mice show that KRAS G12C inhibitors induce a pro-inflammatory phenotype in the tumor microenvironment of LUADs, which can be further exploited with targeted anti-PD-1 therapy." (PMID 35205778, 2022). "They showed that only a small portion of dormant tumor cells survived KRAS ablation (called surviving cells, SCs), and these cells had stem-like characteristics and were responsible for tumor relapse." (PMID 36497394, 2022). "Low tumor-infiltrating lymphocyte density, KRAS alteration, and chromosomal instability are related to immune-suppressive tumor microenvironments with resistance to programmed death 1/ programmed death ligand 1 blockade." (PMID 35433771, 2022). "A heatmap was constructed to show the relationships between mitophagy genes and the LUAD clinical factors that comprised age, gender, T stage, M stage, N stage, tumor stage, and KRAS status." (PMID 36612054, 2022). "This was initially observed in a mouse model of PDAC, where genetic ablation of KRAS or pharmacological inhibition of the MAPK pathway led to rapid tumor shrinkage, while a small population of PDAC cells survived." (PMID 36139512, 2022). "KRAS was the most frequently altered oncogene with alterations identified in 97,062 (23%) pan-tumor tissue samples." (PMID 36494601, 2022). "Genetic knockout of Shoc2 suppresses the growth of a subset of KRAS-mutant cancer cell lines and inhibits tumour growth in mouse models of KRAS-driven lung cancer, demonstrating that SHOC2 function is critical for RAS–RAF pathway activation." (PMID 35768504, 2022). "There are two subclasses of CIMP tumours: CIMP-high tumours (or CIMP1) have BRAF mutations and are microsatellite-unstable; CIMP-low (or CIMP2) tumours have KRAS mutations." (PMID 35055034, 2022). "Cytokines produced by Th2, particularly IL-4 and IL-13, can not only reduce anti-tumor immune responses, but also can directly accelerate tumor growth induced by KRAS transformed cells." (PMID 36408139, 2022). "In a KRAS-specific context, the role of KRAS signaling on the tumor microbiome is still to be determined, even though, it is accepted that the exposure to bacterial can shape the development of CRC of which KRAS can be one major player." (PMID 36344948, 2022).
tumor (continued). "In common tumor types including NSCLC, CRC and PDAC, KRAS mutation frequencies and hotspot mutation clusters were confirmatory of published literature." (PMID 36494601, 2022). "We further detected KRAS mutations in 71 surrounding endometrial tissues of PPE, which included 48 non-hyperplastic, 7 concurrent hyperplasia, and 16 concurrent neoplasia (11 EAH and 5 carcinoma) tissues." (PMID 35796805, 2022). "These insights have thus led to several clinical trials specifically targeting tumor metabolism in KRAS/NRF2 tumors." (PMID 35626147, 2022). "As a point of interest, we also investigated the association between tumor budding and molecular biomarkers, such as MSI status, KRAS, and NRAS mutations." (PMID 35096426, 2022). "Additional pathogenic mutations, including KRAS p.(Ala59Thr), PIK3CA p.(Thr1025Ala), and PIK3R2 p.(Lys564Glu), were identified in that particular stage-3 specimen, suggesting that the tumor is refractory to the anti-HER2 treatment." (PMID 36612265, 2022). "GINS3, a KRAS-inactivated subtype, was featured by high tumor purity, immune-desert, activation of EGFR and ephrin receptors, CIN, fewer KRAS mutations, and SMOC1 methylation." (PMID 36345721, 2022). "Inhibition of cell cycle genes in vivo in MRTX849-treated xenografts intensified further tumor growth inhibition over the effects of KRAS inhibition alone." (PMID 35922812, 2022). "The tumor suppressor function of miR-217 is performed by directly targeting KRAS, since miR-217 overexpression has been correlated with reduced KRAS levels." (PMID 35599791, 2022). "Western blot analysis revealed KRAS knockdown in xenograft tumours after αEGFR-mAB-P/KRAS-siRNA/P nanostructure treatment." (PMID 35220407, 2022). "Oncogenic KRAS G12D signaling in tumor cells regulates the signaling of surrounding stromal cells and establishes reciprocal signaling between tumor and stromal cells." (PMID 36531078, 2022). "Genetic or pharmacologic suppression of PGM3 reduced KRAS/LKB1 co-mutant tumor growth in both in vitro and in vivo settings." (PMID 35011738, 2022). "The presence of well-known mutations reported in genes that commonly occur in EAC, known as driver mutations like ARID1A, CDKN2A, KRAS, APC, SMAD4, and PI3KCA, and a high tumor mutation burden (TMB) level makes EAC a highly heterogeneous disease." (PMID 35328735, 2022). "Sotorasib is a novel targeted inhibitor of Kirsten rat sarcoma (KRAS) (G12C) that has shown exciting tumor-suppressing effects not only for single targeted agents but also for combination with immune checkpoint inhibitors." (PMID 35449573, 2022). "Exploratory baseline circulating tumor DNA (ctDNA) sequencing revealed increased survival for patients with KRAS wildtype tumors in both the combination immunotherapy (p = 0.001) and chemotherapy (p = 0.004) groups." (PMID 36028483, 2022). "Common molecular mutations occur in members of the RAS family (KRAS, NRAS, and HRAS) that cause tumor progression." (PMID 35463728, 2022).